APLN (apelin)
Diseases named in the same sentence as APLN in open-access papers (continued):
Sharing a sentence is not in itself a finding about the gene and the disease.
Obesity (continued). "Given this insulin-sensitizing property, apelin has become a promising therapeutic target for treating obesity and diabetes." (PMID 31718027, 2019). "Observational human studies have confirmed the presence of increased apelin concentrations in type 2 diabetes mellitus and obesity, and they have raised the possibility of its use as a biomarker." (PMID 31492821, 2019). "This study discussed the idea that patients with higher body mass indices and decompensated HF displayed lower in-hospital mortality, while apelin is also increased in these patients with obesity patients." (PMID 31492821, 2019). "For example, increase levels of Apelin-12 in colon cancer patients with obesity, or elevated levels of apelin-36 in endometrial and breast cancer patients with obesity have been found." (PMID 32039239, 2019). "Long-term treatment with acylated analogs of apelin-13 amide [particularly pGlu(Lys8GluPAL)apelin-13] ameliorated diet induced obesity-diabetes in mice and improved lipid profile." (PMID 31492821, 2019). "Apelin levels were found to be increased in type II diabetes and hyperinsulinemia-dependent obesity and decreased in hypertension and hypertensive heart disease." (PMID 30864627, 2019). "In animal models, apelin-transgenic mice were resistant to diet-induced obesity via stimulating energy expenditure and administration of apelin-13 (a truncated apelin peptide with 13-amino acid) decreased body adiposity in diet-induced obese mice." (PMID 31217908, 2019). "Plasma apelin concentration is increased in people with obesity 9, T2D patients 10 and hyperinsulinemic obese mice." (PMID 30868058, 2019). "Recent studies demonstrated that apelin is involved in energy metabolism and the pathophysiology of obesity." (PMID 30526660, 2018). "Consistent with this view, recent work in our laboratory has shown that therapeutic natural and stable analogues of apelin-13 stimulate insulin secretion, enhance cellular glucose uptake and improve acute glucose tolerance in animal models of obesity-diabetes." (PMID 30157220, 2018). "Numerous studies indicate an emerging involvement of apelin in energy metabolism and the pathophysiology of obesity." (PMID 30157220, 2018). "In clinical and experimentalstudies, serum levels of Apelin or its adipose tissueexpression are increased in case of obesity and insulinresistance." (PMID 29845798, 2018). "This highlights possible values of apelin/APJ interactions as an intriguing therapeutic target for obesity and diabetes." (PMID 30157220, 2018). "When diet induced obesity-diabetes was established after high-fat feeding, mice were injected i.p. once daily with apelin analogues, liraglutide (25 nmol/kg) or saline (controls)." (PMID 30157220, 2018). "Circulating apelin concentrations are increased in obese humans and rodent models of obesity only when accompanied by hyperinsulinaemia." (PMID 30157220, 2018). "Apelin is a myokine involved in the pathophysiology of obesity, IR, diabetes mellitus type 2 and cardiovascular function." (PMID 29482601, 2018). "Previous studies have suggested that circulating apelin was correlated directly with obesity, and in a broader sense, with obesity-related cardiovascular events." (PMID 28915675, 2017). "By obesity status in controls, the reduction in circulating apelin concentration was comparable between studies with normal weight controls (BMI < 25 kg/m2) (WMD: -1.336 ng/mL, P < 0.001) and obese controls (BMI ≥ 25 kg/m2) (WMD: -1.226 ng/mL, P = 0.007)." (PMID 28915675, 2017). "Apelin is upregulated in the adipose tissues of obese subjects; thus, plasma apelin concentration is increased in obesity and metabolic disease." (PMID 28422056, 2017). "Only 5 polymorphisms in apelin/APJ system were significantly associated with hypertension, obesity and onset age of hypertension." (PMID 27863393, 2016).
Obesity (continued). "Our work suggests that the KCNQ channels in POMC neurons would be an alternative therapeutic target against obesity and type 2 diabetes as they are regulated by anorexigenic neurotransmitters and adipokines such as serotonin and apelin." (PMID 25782002, 2015). "Perhaps the most significant finding from our study is that post-treatment with apelin preserves mitochondrial ultrastructural integrity and increases mtDNA content in conditions combining I/R injury and obesity." (PMID 26542760, 2015). "In a mouse model combining ischemia-reperfusion (I/R) injury and high-fat diet (HFD)-induced obesity, we identify apelin as a novel regulator of FoxO3 trafficking in cardiomyocytes." (PMID 26542760, 2015). "Apelin is an adipocytokine known for its anti-obesity and anti-diabetic properties, Apelin promotes the expression of anti-oxidant enzymes and suppresses the expression of pro-oxidant enzyme via AMPK pathway." (PMID 25963634, 2015). "More recently, chronic apelin treatment has also been shown to prevent reduction of fatty acid and glucose oxidation in a model of obesity-related decline of cardiac function." (PMID 25914650, 2015). "In animal experiments, it is shown that apelin secretion by adipocytes and plasma apelin levels increase in hyperinsulinemia related obesity." (PMID 25374607, 2014). "Correlations between apelin and insulin resistance, a major characteristic of obesity and type 2 diabetes, have been demonstrated by several authors." (PMID 24475149, 2014). "Our results showed significantly higher TC, TG, LDL-C, insulin, and HOMA-IR in all obese subjects versus non-obese controls, but results vary among other international studies of apelin and obesity-related markers." (PMID 24475149, 2014). "The up-regulation of apelin in obesity can contribute to endocrine or metabolic dysfunctions, such as diabetic retinopathy." (PMID 23874984, 2013). "We demonstrated that T2D is a determinant of increased circulating apelin levels independently from the concomitant presence of obesity and other metabolic alterations." (PMID 23227256, 2012). "Apelin has been identified as a novel adipokine, which is upregulated by obesity and hyperinsulinemia in both humans and mice." (PMID 22197493, 2012). "Currently some evidence supports a relationship between insulin resistance (IR) and hepatitis C on one hand, playing role in progression of liver disease, and between IR and apelin level on the other hand in cases of obesity." (PMID 22007137, 2011). "Elevated serum apelin levels have been observed in individuals with obesity." (PMID 41562846, 2026). "A Polish study showed that apelin concentrations were significantly lower in a group of women with Anorexia nervosa compared to a control group with normal BMI and a group of women with obesity." (PMID 40491594, 2025). "Under heightened inflammation conditions, such as obesity or diabetes, apelin-13 at a concentration of 20 nM may also influence the hypothalamic regions in mice, leading to the production of ROS." (PMID 40177358, 2025). "Whether targeting apelin can also mitigate obesity- and aging-related disorders requires further investigation." (PMID 40612675, 2025). "English-language publications were included by searching the database - PubMed, ScienceDirect, EMBASE, using the terms - adolescent girls, PCOS, adipokines, leptin, adiponectin, resistin, apelin, vaspin, visfatin, ghrelin, omentin, obesity, insulin resistance, metabolic syndrome." (PMID 40491594, 2025). "However, in a subgroup analysis, they observed reduced apelin-36 levels in patients with obesity, PCOS and elevated levels in the normal-weight group, compared with the control group." (PMID 40491594, 2025). "The increased systemic apelin concentrations in diabetes and obesity may be explained by its compensation for the reduced insulin sensitivity in T2DM." (PMID 39189510, 2024).
Obesity (continued). "In addition, in females with obesity, apelin-12 concentrations decreased after 2 months of aerobic and resistance exercise." (PMID 39519480, 2024). "Though not implicated in GWAS, apelin and its receptors are involved in energy metabolism and obesity." (PMID 38167462, 2024). "A number of studies suggested that apelin levels in plasma may be elevated in obesity and type 2 diabetes." (PMID 39457235, 2024). "In addition, studies have demonstrated decreased apelin concentrations after weight loss due to diet, exercise or bariatric surgery, indicating a reverse regulation of apelin in obesity." (PMID 39519480, 2024). "Some studies found that injecting apelin systemically or centrally in normovolemic animals increased water intake, while others found that injecting apelin centrally in animals with HFD-induced obesity or water deprivation decreased water intake and VP plasma levels." (PMID 37424869, 2023). "This study was undertaken to find a correlation between Apelin, IR, and obesity." (PMID 37706122, 2023). "However, due to the complexity in the relationship between the pathophysiology of obesity and apelin signaling, the role of apelin in MSC dysfunction during obesity remains to be further investigated." (PMID 36750692, 2023). "Apelin plays protective role in obesity, by regulating the inflammation and oxidative stress." (PMID 37886639, 2023). "Accordingly, exogenous apelin injection restored glucose tolerance and increased glucose utilization in peripheral tissues in high fat diet mice with hyperinsulinemia, hyperglycemia, and obesity." (PMID 36902176, 2023). "However, with respect to the periodontium, almost nothing is known about the production, regulation, and action of apelin, another adipokine whose serum levels are altered in obesity." (PMID 36902162, 2023). "Higher concentrations of apelin have been found in pregnant women with obesity during pregnancy, which could explain their decreased myometrial contractility, potentially due to the inhibition of the myometrial RhoA/ROCK (RhoA kinase) pathway." (PMID 37175743, 2023). "When patients had concomitant periodontitis and obesity, apelin levels were highest." (PMID 36902162, 2023). "The studies on Apelin and its relation to IR and obesity in T2DM is recent and very sparse." (PMID 37706122, 2023). "Apelin and chemerin are newly identified adipokines, which are higher in obesity and diabetes." (PMID 36714603, 2023). "In cases of obesity, both adipose tissue and plasma apelin levels are elevated." (PMID 38001998, 2023). "In conclusion, Apelin-13, which is an adipokine, might play a heterogeneous role in the regulation of different pathological states, such as obesity, diabetes, osteoporosis, and other metabolic diseases." (PMID 38089606, 2023). "Hence, exercise and apelin are known as regulators of energy metabolism and have anti-obesity and anti-diabetic properties." (PMID 36093083, 2022). "Moreover, our results indicated that in subjects with hypertension and obesity, apelin levels are also lower than normal." (PMID 36352477, 2022). "Apelin is produced by fat tissue and muscles and decreased in obesity." (PMID 35008925, 2022). "Another animal experiment also showed that apelin-13 regulates the expression of PPARγto inhibit adipogenic differentiation and regulates the expression of perilipin to promote lipolysis, thereby reducing obesity." (PMID 35355561, 2022). "In this review, we summarized the literatures on the role of the apelin–APJ system in diabetes and obesity, and we hope for further research that will establish their role as a new diagnostic marker or therapeutic agent in diabetes and obesity." (PMID 35355561, 2022). "Hence, apelin is known as a regulator of energy metabolism and has anti-obesity and anti-diabetic properties." (PMID 36093083, 2022).
Obesity (continued). "The lower apelin and nitric oxide levels in patients with hypertension and obesity or their reduction due to infection with COVID-19 or concomitant COVID-19 + diabetes mellitus may make them vulnerable to experiencing severe diseases." (PMID 36352477, 2022). "Apelin can inhibit fat cell differentiation, enhance lipolysis and improve obesity." (PMID 36093083, 2022). "The over-expression of hypothalamic apelin was observed in obesity and diabetes." (PMID 35355561, 2022). "In diabetes or obesity with hyperinsulinemia, apelin levels increase." (PMID 36093083, 2022). "Therefore, apelin probably will be considered an important target for the treatment of obesity-related insulin resistance." (PMID 36077676, 2022). "(Section 2), insulin enhances apelin expression in human and mouse adipocytes, suggesting the existence of a regulating loop that may promote apelin secretion during obesity as a compensatory mechanism to adapt to enhanced insulin requests." (PMID 35628332, 2022). "This peptide was shown to decrease triglycerides accumulation in hypertrophic adipocytes in vitro through AQP7 mRNA and protein upregulation via PI3K signaling pathway, revealing that apelin-13 is a promising starting point to develop novel treatments against obesity and related health problems." (PMID 35187089, 2022). "Therefore, in this study, the direct role of apelin through maternal exercise on common pregnancy complications such as obesity, gestational diabetes, gestational hypertension, and cardiac hypertrophy is investigated." (PMID 36093083, 2022). "In obesity, as one of the important risk factors of CVD, dysregulation of adipokines such as apelin originating from adipose tissue may result in the association between obesity and CVD." (PMID 35913970, 2022). "Thus, apelin can be a new therapeutic target for obesity and metabolic diseases in children of obese mothers." (PMID 36093083, 2022). "In addition, a new study would allow us to refine our model by including other obesity-related parameters such as insulin sensitivity and circulating levels of apelin expression." (PMID 33972642, 2021). "Therefore, in the context of obesity, apelin expression seems essential to preserve vascular homeostasis." (PMID 34782679, 2021). "Our studies also pointed to higher levels of apelin in the preeclampsia subgroup with obesity." (PMID 34577885, 2021). "When comparing the level of apelin in the plasma of people with morbid obesity and healthy people, the former group presented statistically significant hormone overproduction that occurred only in people with obesity as well as type II diabetes." (PMID 35011661, 2021). "Further investigation on the effects of apelin on food intake may provide new ideas for the treatment of obesity." (PMID 33679444, 2021). "The inflammatory markers TNF-α and hypoxia-inducible factor 1-alpha (HIF-1α) regulate apelin secretion and it is speculated that apelin has a role in anti-inflammatory pathways in obesity." (PMID 33327460, 2020). "We next tested whether obesity‐related levels of apelin could also influence TNBC metastasization in addition to an increase in primary TNBC tumour growth." (PMID 32681609, 2020). "Apelin signaling is also involved in many physiological processes such as energy metabolism, blood pressure regulation, and cardiac contractility and plays an important role in organ and tissue pathologies including DM, obesity, HF, and HIV-1 infection." (PMID 33233425, 2020). "One contributing factor to tumour growth in obesity could be the modulation of apelin expression as it is increased in obese mice showing large TNBC tumours but unaffected in HFD‐fed mice showing normal TNBC tumours." (PMID 32681609, 2020). "APLN plays an integral role in the obesity/adipokine/adipokine-induced angiogenesis–OA network." (PMID 32131466, 2020). "Several mechanisms have been proposed to investigate the role of apelin in resisting obesity." (PMID 32998691, 2020).
Obesity (continued). "While apelin is involved in the regulation of food intake, energy metabolism, cardiovascular system and neuroendocrine functions, it has also been described as a beneficial adipokine related to obesity functions." (PMID 32998691, 2020). "Hyperinsulinemia induces high circulating apelin levels in obesity." (PMID 33379163, 2020). "We suggest that apelin is a critical driver of obesity‐induced TNBC progression." (PMID 32681609, 2020). "Another possibility could be that the apelin infusion used in this study cannot account for all effects on the apelinergic system in obesity conditions." (PMID 32681609, 2020). "We hypothesize that apelin, an adipokine whose levels are increased in obesity, could be a major factor contributing to both tumour growth and metastatization in TNBC obese patients." (PMID 32681609, 2020). "Apelin is another adipokine whose levels are increased with obesity." (PMID 32681609, 2020). "Moreover, increased plasma apelin levels were found in individuals with obesity as well as in those with type 2 diabetes." (PMID 33192583, 2020). "Therefore, the findings from the present study are in line with these previous studies that low levels of apelin are likely to lead to obesity." (PMID 32998691, 2020). "Because elevated inflammatory cytokines in obesity can accelerate the expression and secretion of apelin, it is hypothesized that downregulation of apelin in obese diabetic rats treated with LC may be associated with the anti‐inflammatory action of LC." (PMID 33278072, 2020). "This study investigated the endurance exercise-induced changes in lesser known adipokines (visfatin, chemerin, apelin, semaphorin 3 C) related to obesity and metabolism, and their correlations with the changes in the parameters of obesity and glucose homeostasis." (PMID 32561824, 2020). "However, in apparent contrast, Apelin enhances lymphatic and blood vessel integrity in ischemic conditions, and in obesity, it blocks an increase in permeability induced by dietary fatty acids." (PMID 31318171, 2019). "Furthermore, mounting evidence has indicated a predictive role for single nucleotide polymorphisms (SNPs) in the apelin-APJ system for incident hypertension, obesity phenotype and insulin resistance." (PMID 31217908, 2019). "Chronic apelin treatment (two to four weeks) improves insulin sensitivity, lowers blood glucose levels, and protect the animals from hyperinsulinemia and glucose intolerance in mice with obesity or insulin resistance." (PMID 31718027, 2019). "Apelin is a recently discovered adipokine that has been reported to improve sugar intake and insulin sensitivity, to promote energy consumption, and to reduce blood pressure, while also being important in obesity-related metabolic disease." (PMID 30696454, 2019). "Still, Apelin/APJ have been implicated in many physiological processes including cardiac function, body fluid homeostasis, angiogenesis, and energy metabolism with bearing for pathological conditions such as heart failure, obesity, diabetes, and cancer." (PMID 31318171, 2019). "Interestingly, some adipokines that have beneficial effects on carbohydrate metabolism, such as visfatin, vaspin, and apelin, are paradoxically upregulated in obesity, possibly to partially compensate for the obesity-induced metabolic abnormalities." (PMID 30823446, 2019). "Apelin, as a member of the adipose tissue-derived peptides, might contribute to obesity-related disorders." (PMID 29875677, 2018). "Altered serum apelin levels have been detected in multiple tissues under obesity and diabetes and could be a therapeutic target in the treatment of this pathologies." (PMID 29875677, 2018). "Apelin, which belongs to the adipokines family, also plays a role in obesity." (PMID 30127323, 2018). "However, the findings of studies investigating the role of apelin in obesity are inconsistent, and there are still many gaps in this topic." (PMID 29875677, 2018).